C2orf42 (chromosome 2 open reading frame 42)
Synonyms: FLJ20558
Tractability: PROTAC: its protein half-life has been measured.
Gene: Protein-coding gene on chromosome 2 (70,149,882 to 70,248,615, reverse strand). Ensembl gene ENSG00000115998.
Subcellular location (Human Protein Atlas): Nucleoplasm
Gene Ontology:
Molecular function: protein binding
Cellular component: nucleoplasm; nucleus
Genetic constraint (gnomAD): Loss-of-function variants: 19 observed, 28.58 expected, observed/expected ratio (o/e) 0.66, 90% interval 0.46 to 0.98. The upper end of that interval is the gene's LOEUF score, 0.98, which puts it in group 4 of 6, group 1 being the genes least tolerant of losing a copy. Missense variants: 423 observed, 476.88 expected, observed/expected ratio (o/e) 0.89, 90% interval 0.82 to 0.96. Synonymous variants: 158 observed, 189.92 expected, observed/expected ratio (o/e) 0.83, 90% interval 0.73 to 0.95.
Homologues: Orthologues: chimpanzee C2AH2orf42 (100% identical), macaque C13H2orf42 (99% identical), pig C2orf42 (98% identical), rabbit C2orf42 (97% identical), dog C2orf42 (96% identical), guinea pig C2orf42 (96% identical), rat C4h2orf42 (93% identical), mouse C87436 (92% identical), tropical clawed frog c3h2orf42 (70% identical), zebrafish C5H2orf42 (50% identical), Drosophila melanogaster CG2321 (22% identical).
Diseases named in the same sentence as C2orf42 in open-access papers:
C2orf42 is named in the same sentence as 1 disease in open-access papers, as found by Europe PMC text mining. Sharing a sentence is not in itself a finding about the gene and the disease. The quoted sentences say what the papers report.
pancreatic cancer (1 paper, 2020). "Human protein atlas also suggests POL3HR and C2ORF42 are favorable prognostic markers in pancreatic cancer." (PMID 32310997, 2020).